IGHD4-4 (immunoglobulin heavy diversity 4-4)
Synonyms: IGHD44; DA4
Gene: Immunoglobulin diversity (D) gene on chromosome 14 (105,913,222 to 105,913,237, reverse strand). Ensembl gene ENSG00000233655.
Diseases named in the same sentence as IGHD4-4 in open-access papers:
IGHD4-4 is named in the same sentence as 1 disease in open-access papers, as found by Europe PMC text mining. Sharing a sentence is not in itself a finding about the gene and the disease.
IGHD4-4 shares sentences with these, for which no sentence is quoted: gastric cancer (1 paper).